RECK (reversion inducing cysteine rich protein with kazal motifs)
Diseases named in the same sentence as RECK in open-access papers (continued):
Sharing a sentence is not in itself a finding about the gene and the disease.
RECK also shares sentences with these, for which no sentence is quoted: esophageal cancer (5 papers); lymph node metastasis (3); colorectal tumour (2); Autoimmunity (1); B-cell lymphomas (1); brain injury (1); cardiac disease (1); Cerebral ischemia (1); cervical intraepithelial neoplasia (1); chronic obstructive pulmonary disease (1); Cognitive impairment (1); diabetic kidney disease (1); diarrheal disease (1); ductal carcinoma in situ (1); eosinophilia (1); epilepsy (1); Epstein-Barr virus infection (1); Ewing sarcoma (1); fibromatosis (1); Hypertension (1); hyperuricemia (1); idiopathic interstitial pneumonia (1); Keratocystic odontogenic tumor (1); kidney disease (1); liver cirrhosis (1); lupus nephritis (1); lymphoma (1); myocarditis (1); nerve sheath tumors (1); non-alcoholic steatohepatitis (1).
A further 17 diseases each share a sentence with RECK in 1 paper.